NEDD4L (NEDD4 like E3 ubiquitin protein ligase)
Diseases named in the same sentence as NEDD4L in open-access papers (continued):
Sharing a sentence is not in itself a finding about the gene and the disease.
melanoma (15 papers, 2020 to 2025). A malignant, usually aggressive tumor composed of atypical, neoplastic melanocytes. "We provide additional experimental evidence that confirms the ability of NEDD4L overexpression to increase BRAFi resistance in a melanoma xenograft model." (PMID 38213996, 2024). "A prior study found that expression of NEDD4L is upregulated in melanomas relative to benign nevi, suggesting a role for NEDD4L in early-stage melanoma progression." (PMID 38213996, 2024). "ERK can phosphorylate NEDD4L on S448, and this phosphorylation is reduced in melanoma cells that are resistant to the RAF inhibitor PLX4720." (PMID 37511580, 2023). "Despite its low expression in most tumors, NEDD4L is highly expressed in a few, such as Sézary syndrome, melanoma, and invasive gallbladder cancer." (PMID 38027016, 2023). "Another study reported that NEDD4L downregulation inhibited the growth of G361 melanoma cells cultured in vitro, while NEDD4L expression promoted the growth of A2058 melanoma cells in vivo." (PMID 38027016, 2023). "SP1 is identified as a substrate of NEDD4L, and NEDD4L downregulates it via ubiquitination at K685 site, inhibiting the proliferation and metastasis of melanoma mediated by the SP1-integrin αvβ3 pathway." (PMID 38027016, 2023). "NEDD4L overexpression promotes the growth of A2058 melanoma cells in vivo, whereas NEDD4L downregulation reduces the growth of G361 melanoma cells in vitro." (PMID 38027016, 2023). "Overexpression of NEDD4L promoted the growth of A2058 melanoma cells in vivo, and downregulation of NEDD4L reduced the growth of G361 melanoma cells in vitro." (PMID 34869021, 2021). "NEDD4L is an E3 ubiquitin ligase, which can be overexpressed in melanoma and promote tumour growth." (PMID 37511580, 2023). "Further, it was found that in xenograft models, exogenous NEDD4L expression significantly aided the growth of G-361 melanoma cells in vivo, and it was suggested that NEDD4L expression might be elevated in many melanomas to aid tumor growth." (PMID 36293239, 2022). "An in vitro study proved that many melanoma cells show immunoreactivity for NEDD4L, and during the neoplastic transformation of melanocytes, the expression of NEDD4L might rise." (PMID 36293239, 2022). "Emerging evidences have reported that NEDD4L may function as a tumor suppressor that is frequently reduced in human carcinomas of pancreatic, colorectal, melanoma, ovarian and lung." (PMID 34838005, 2021). "Therefore, the role of NEDD4L in the development of melanoma is controversial and needs to be further clarified." (PMID 34869021, 2021). "High level of NEDD4L may contribute to the promotion of melanoma cell growth in vivo." (PMID 39557844, 2024). "NEDD4L ubiquitinates SP1, leading to its degradation, which inhibits melanoma cell proliferation." (PMID 38027016, 2023). "In addition, phosphorylation of NEDD4L is activated by MEK1/2 phosphorylation increased by JP1, a functional polypeptide, ultimately inhibiting melanoma proliferation and metastasis." (PMID 38027016, 2023). "NEDD4L, activated by a functional polypeptide (JP1), induced degradation of SP1 via the ubiquitin-proteasome pathway and then attenuated the transcription of integrin αvβ3 to inhibit cell proliferation and metastasis of melanoma." (PMID 34869021, 2021). "JP1 was targeted to and entered melanoma cells with high expression of integrin αvβ3 by RGD, and then interacted with MEK1/2 to activate E3 ubiquitination enzyme NEDD4L, which accelerated the degradation of SP1 and ultimately played a transcriptional inhibitory role on integrin αvβ3." (PMID 32724456, 2020). "In addition, NEDD4L is expressed in melanoma but not in benign melanocytes and benign nevi tissue." (PMID 38027016, 2023).
pancreatic cancer (15 papers, 2020 to 2025). "Under conditions of nutrient deprivation, NEDD4L knockdown causes the accumulation of SLC1A5 in pancreatic cancer cells and stabilizes its protein level, and NEDD4L depresses autophagy and increases the oxygen consumption rate under cellular metabolic stress." (PMID 37190313, 2023). "The interesting finding was that ASCT2, stabilized by the loss of NEDD4L, exerted an essential role in activating autophagy in NEDD4L-downregulated pancreatic cancer cells, in addition to its direct activity in delivering key substrates for mitochondrial metabolism." (PMID 36918822, 2023). "NEDD4L was demonstrated to be linked to iron metabolism in pancreatic cancer." (PMID 34869021, 2021). "First, we showed that ULK1 associates with NEDD4L in pancreatic cancer cells." (PMID 31959741, 2020). "NEDD4L binds to ULK1 in pancreatic cancer cells and is involved in the ubiquitination and subsequent degradation of ULK1 to downregulate autophagy and mitochondrial metabolism, ultimately suppressing the growth and survival of pancreatic cancer cells." (PMID 38027016, 2023). "Overexpressed NEDD4L was found to repress autophagy in pancreatic cancer cells by decreasing cellular levels of the autophagy protein ULK1 and the glutamine transporter ASCT2." (PMID 36918822, 2023). "LINC00941 interacts with ANXA2 and inhibits NEDD4L-mediated ANXA2 degradation to promote cell proliferation in pancreatic cancer." (PMID 38027016, 2023). "MicroRNA-23A (miR-23A) inhibits the expression of NEDD4L to collaborate with miR-21 and miR-27A, thus promoting the progression of pancreatic cancer." (PMID 34869021, 2021). "Mounting studies have discovered that NEDD4L plays a pivotal role in the development of pancreatic cancer." (PMID 34869021, 2021). "N-myc downstream regulated gene-1 (NDRG1), an iron-regulated metastasis suppressor, upregulated the expression of NEDD4L in PANC1 pancreatic cancer cells." (PMID 34869021, 2021). "Specifically, pancreatic cancer cells with low levels of NEDD4L predominantly relied on the activation of autophagy and mitochondrial OXPHOS for cancer growth and survival in both in vitro and in vivo studies." (PMID 31959741, 2020). "In a mouse xenograft model of pancreatic cancer, the use of autophagy inhibitors suppressed tumor growth more in NEDD4L-depleted cells than in tumors from control cells." (PMID 31959741, 2020). "It was found that the growth rate of NEDD4L-knockdown conditions was higher than control in various pancreatic cancer cells." (PMID 31959741, 2020). "Therefore, NEDD4L acts as a tumor-suppressor protein to inhibit the proliferation and survival of pancreatic cancer cells by ubiquitinating SLC1A5 expression." (PMID 37190313, 2023). "N-Myc downstream-regulated gene-1 (NDRG1), a tumor-suppressor gene, inversely correlates with tumor progression in a variety of tumors, including pancreatic cancer, and NDRG1 enhances the expression of NEDD4L in pancreatic cancer cells, which plays a role in degrading carcinogenic pSMAD2L." (PMID 38027016, 2023). "In addition to miR-629-5p, miR-23a was shown to promote the progression of pancreatic cancer via targeting NEDD4L." (PMID 37580757, 2023). "NEDD4L mediates the degradation of the iron-binding transport protein lactotransferrin (LTF) by ubiquitination to hinder the malignant biological behavior of pancreatic cancer." (PMID 34869021, 2021). "However, the genetic or pharmacological blockade of either ULK1 or ASCT2 in NEDD4L-depleted cells sensitized pancreatic cancer cells, particularly in response to nutrient deprivation." (PMID 31959741, 2020). "To investigate this hypothesis, we examined whether NEDD4L depletion would influence cell growth or survival in pancreatic cancer cells." (PMID 31959741, 2020). "Hence, NEDD4L acts as a tumor-suppressor gene in pancreatic cancer." (PMID 34869021, 2021).
pancreatic cancer (continued). "We discovered that in pancreatic cancer, LINC00941 acts as a protein decoy in the cytoplasm and confirmed that it can competitively bind to the E3 ubiquitin ligase NEDD4L to inhibit the ubiquitination of ANXA2 and promote its stabilization." (PMID 35977942, 2022). "Ubiquitination by NEDD4-like E3 ligase (NEDD4L) in pancreatic cancer cells promoted ULK1 degradation, while NEDD4L depletion activated autophagy by stabilizing ULK1, which in turn supported cancer progression and survival." (PMID 34502089, 2021). "NEDD4L and ULK1 levels were inversely correlated in two different pancreatic cancer mouse models-xenograft mouse and KPC mouse models." (PMID 31959741, 2020). "In human pancreatic cancers, more than 15% of Cancer Cell Line Encyclopedia (CCLE; gepia.cn) datasets showed the down-regulation of Nedd4l gene expression." (PMID 31959741, 2020). "ULK1 has been shown to be involved in the generation of its autophagy in many diseases, for example, in pancreatic cancer, NEDD4L can interact with ULK1 to reduce ULK1 expression to inhibit autophagy and mitochondrial metabolism, which in turn inhibits the survival of pancreatic cancer cells." (PMID 38887520, 2024). "Further, NEDD4L was found to inhibit ULK1- and ASCT2-mediated mitophagy whereby suppressing adequate fuel supplementation via mitochondrial metabolism, leading to inducing cell death and inhibiting tumor growth in pancreatic cancer cells." (PMID 36918822, 2023). "Here, we show that NEDD4L, an E3 ubiquitin ligase, binds ULK1 in pancreatic cancer cells." (PMID 31959741, 2020). "Therefore, these overall results support the critical role of NEDD4L in deregulating the protein stability of ULK1 and ASCT2, thereby effectively diminishing autophagy and further repressing pancreatic cancer growth." (PMID 31959741, 2020). "First, glutamine uptake was investigated in the absence of NEDD4L in pancreatic cancer cells using an extracellular metabolite analyzer." (PMID 31959741, 2020). "Of note, it was shown that NEDD4L, through inhibiting autophagy, impaired mitochondrial metabolism by disrupting the cellular oxygen consumption rate (OCR), the mitochondrial membrane potential (MMP), and mitochondrial morphology to ultimately suppress pancreatic tumor growth." (PMID 36918822, 2023). "Besides, NEDD4L impeded autophagy and cancer cell proliferation by being involved in the degradation of ULK1, and weakening the expression of the glutamine transporter ASCT2 by the ubiquitination pathway in pancreatic cancer." (PMID 34869021, 2021). "To determine the effect of NEDD4L-mediated autophagy inactivation on pancreatic cancer progression, we compared tumor growth in in vivo xenograft mice models administered with human pancreatic cancer cell line MIA PaCa-2 with (shNEDD4L) or without (shCTL) NEDD4L knockdown." (PMID 31959741, 2020). "As NEDD4L, a newly identified ULK1-interacting protein, is a well-known E3 ubiquitin protein ligase, the modulation of ULK1 levels in the presence or absence of NEDD4L were next examined in pancreatic cancer cell lines." (PMID 31959741, 2020).
pulmonary fibrosis (13 papers, 2020 to 2025). Chronic progressive interstitial lung disorder characterized by the replacement of the lung tissue by connective tissue, leading to progressive dyspnea, respiratory failure, or right heart failure. "NEDD4L plays an important role in normal functioning of pulmonary epithelial cells, and its dysfunction causes pulmonary fibrosis." (PMID 34198949, 2021). "NEDD4L alleviates experimental pulmonary fibrosis by targeting ubiquitination of TGFBR2 in lung fibroblasts." (PMID 38267743, 2024). "And knockout of nedd4l accelerates the progression of pulmonary fibrosis." (PMID 41516261, 2025). "In this sense, we speculated that NEDD4L may regulate the progression of pulmonary fibrosis through the CTHRC1/HIF-1α signal axis." (PMID 34512149, 2021). "The deletion of NEDD4L exacerbates IPF in murine models, underscoring its protective role in bleomycin-induced pulmonary fibrosis by mediating the degradation of ENaC and TβR." (PMID 40901482, 2025). "Thus, we speculated that NEDD4L might regulate the progression of pulmonary fibrosis." (PMID 34512149, 2021). "To validate our speculation that NEDD4L may modulate pulmonary fibrosis through the CTHRC1/HIF-1α signal axis, we performed Pearson correlation analysis on 35 lung tissue of IPF and revealed the negative correlation between the expression of NEDD4L and CTHRC1." (PMID 34512149, 2021).
Liddle syndrome (10 papers, 2007 to 2022). A rare genetic form of low-renin hypertension characterized by hypertension associated with decreased plasma levels of potassium and aldosterone. "Mutation in this PY motif, which is also the binding site for the ubiquitin ligase Nedd4L, might cause Liddle syndrome." (PMID 35429991, 2022). "Genetic analyses of the Liddle syndrome and hereditary hypertension found that ENaC, which is restricted to the terminal nephron and regulates sodium reabsorption, and its regulatory protein, NEDD4L, are promising candidate genes (NEDD4L) associated with salt-sensitive hypertension." (PMID 32485919, 2020). "Genetic analyses of representative familial hereditary hypertension, known as Liddle syndrome, showed that the Proline-Tyrosine (PY) motif in the C terminus of ENaCs are commonly mutated, resulting in impaired protein-protein interactions with the Nedd4L Tryptophan-Tryptophan (WW) domain." (PMID 28604611, 2017). "Combining these observations with those that demonstrate that ENaC is ubiquitinated by NEDD4L and that NEDD4L and ENaC expression in the ASDN overlap suggested a mechanism that underlies Liddle syndrome." (PMID 19364400, 2009).
ovarian carcinoma (10 papers, 2015 to 2024). A malignant neoplasm originating from the surface ovarian epithelium. "DDB2 enhances TGF-β signal transduction by downregulating NEDD4L transcription to inhibit ovarian cancer cell proliferation." (PMID 38027016, 2023). "For example, DNA damage-binding protein 2 (DDBP2) modulates the responsiveness of ovarian cancer cells to TGF-β-induced growth suppression through NEDD4L." (PMID 36293239, 2022). "Few studies have investigated the independent effect of NEDD4L on ovarian cancer, and more research needs to be carried out." (PMID 34869021, 2021). "The expression of NEDD4L was reduced in invasive ovarian cancer tissues in sharp contrast to that in normal ovarian epithelial tissues." (PMID 34869021, 2021). "Here, we report that DDB2-mediated NEDD4L downregulation endowed a significant impact on ovarian cancer cell proliferation through TGF-β signal transduction." (PMID 26130719, 2015). "NEDD4L has emerged as an interesting and important target gene of DDB2 as it is found to be associated with the prognosis of ovarian cancer patients." (PMID 26130719, 2015). "Our findings have revealed, for the first time, that DDB2 is actively involved in regulating the response of ovarian cancer cells to TGF-β stimulation via NEDD4L." (PMID 26130719, 2015). "Taken together, these data indicate that NEDD4L is a target gene of DDB2 and DDB2 is capable of downregulating NEDD4L in ovarian cancer cells." (PMID 26130719, 2015). "The study has uncovered an unappreciated regulatory mode that hinges on the interaction between DDB2 and NEDD4L in human ovarian cancer cells." (PMID 26130719, 2015). "Moreover, NEDD4L knockdown sensitized ovarian cancer cells to erastin- or RSL3-induced cell death and tumor suppression." (PMID 36293239, 2022). "This suggests that the downregulation of NEDD4L protein expression might contribute to the emergence of ovarian cancer." (PMID 36293239, 2022). "Having established that DDB2 is responsible for NEDD4L transcription repression in human ovarian cancer cells, we asked whether this might be translated into alteration in TGF-β signaling and responses of target genes." (PMID 26130719, 2015). "NEDD4L, which is transcriptionally repressed by DDB2, enhances TGF-β signaling in human ovarian cancer cells, ultimately inhibiting ovarian cancer cell proliferation." (PMID 38027016, 2023). "For instance, DNA damage-binding protein 2 (DDB2) suppresses the expression of NEDD4L and then affects the transforming growth factor-β (TGF-β) signaling in ovarian cancer." (PMID 34869021, 2021). "Next, we used another human ovarian cancer cell line PEO1 to further examine the coordination between DDB2 and NEDD4L in the regulation of TGF-β signaling transduction." (PMID 26130719, 2015). "To further confirm the negative regulation of NEDD4L expression by DDB2, we transiently transfected DDB2-expressing constructs into CP70 and SKOV3 ovarian cancer cell lines and showed that NEDD4L was downregulated at both protein and mRNA levels." (PMID 26130719, 2015). "DDB2 could attenuate the expression of NEDD4L and then stimulate TGF-β signaling to inhibit the proliferation of ovarian cancer cells." (PMID 34869021, 2021). "In an ovarian cancer cell model, DDB2 is reported to negatively regulate NEDD4L (Neural precursor cell expressed developmentally downregulated gene 4-like) cellular levels by inducing histone H3 trimethylation at the NEDD4L promoter region." (PMID 31635251, 2019). "Given that NEDD4L plays an important role in constraining transforming growth factor β signaling by targeting activated Smad2/Smad3 for degradation, we investigated the role of DDB2 in the regulation of TGF-β signaling in ovarian cancer cells." (PMID 26130719, 2015). "Thus, by regulating NEDD4L expression, DDB2 enters as a key upstream regulator of the TGF-β signaling cascade in ovarian cancer cells." (PMID 26130719, 2015).
ovarian carcinoma (continued). "In ovarian cancer tissues, NEDD4L protein expression is found to be lower than non-cancer tissues." (PMID 36293239, 2022). "Given that NEDD4L is the principle ubiquitin ligase targeting activated Smad2/3 to constrain the signaling capacity of the TGF-β pathway, it is likely that NEDD4L impacts the progression of ovarian cancer through compromising the responsiveness of cancer cells to TGF-β stimulation." (PMID 26130719, 2015).
lung adenocarcinoma (8 papers, 2021 to 2024). A carcinoma that arises from the lung and is characterized by the presence of malignant glandular epithelial cells. "EGFR signaling can promote the proliferation of lung adenocarcinoma by downregulating the E3 ligase NEDD4L." (PMID 39075515, 2024). "NEDD4L inhibited lung adenocarcinoma cell progression in vitro and in vivo via inducing the ubiquitination‐mediated Ubiquitin‐conjugating enzyme E2T (UBE2T) degradation, which repressed PI3K‐Akt signalling." (PMID 38526036, 2024). "Although the role of NEDD4L in the pathogenesis of lung adenocarcinoma (LUAD) has been described, the mechanism by which NEDD4L promotes LUAD progression remains poorly understood." (PMID 35646490, 2022). "To explore the function of NEDD4L in lung adenocarcinoma, we carried out the following cytological experiments." (PMID 35090513, 2022).